RPL23AP53 (ribosomal protein L23a pseudogene 53)
Gene: Transcribed processed pseudogene on chromosome 8 (213,251 to 213,707, reverse strand). Ensembl gene ENSG00000223508.
Diseases named in the same sentence as RPL23AP53 in open-access papers:
RPL23AP53 is named in the same sentence as 2 diseases in open-access papers, as found by Europe PMC text mining. Sharing a sentence is not in itself a finding about the gene and the disease. The quoted sentences say what the papers report.
tumor (2 papers, 2018 to 2020). "Notably, SRRM2‐AS1, ATP1A1‐AS1 and RPL23AP53 were involved in TNM stages and tumor metastasis." (PMID 29522273, 2018).
RPL23AP53 also shares sentences with these, for which no sentence is quoted: breast carcinoma (1 paper).